MAPT (microtubule associated protein tau)
Diseases named in the same sentence as MAPT in open-access papers (continued):
Sharing a sentence is not in itself a finding about the gene and the disease.
glioma (18 papers, 2019 to 2025). A benign or malignant brain and spinal cord tumor that arises from glial cells (astrocytes, oligodendrocytes, ependymal cells). "For ANXA5, STAT1, CD44, CAV1, and ANXA2, LGG patients with high expression possessed a worse overall survival, while low expression of MAPT was associated with poor overall survival among patients with primary gliomas." (PMID 40607003, 2025). "Among these genes, there is the highest association between high Tau/MAPT expression and many markers of longer life in patients with gliomas." (PMID 39015316, 2024). "A possible connection between cancer and ND is highlighted in a recent study demonstrating that the expression of macrotubule-associated protein (Tau/MAPT), aggregated when excessively phosphorylated in AD, correlates to glioma growth arrest." (PMID 36601538, 2022). "The Microtubule-Associated Protein Tau is expressed in several cancers, including low-grade gliomas and glioblastomas." (PMID 34830972, 2021). "have reported that high MAPT expression is not only related to IDH mutation status but also may aid in the prevention of glioma by disrupting tumor invasion." (PMID 40607003, 2025). "Some studies using the TCGA database found that MAPT gene expression was closely related to survival of patients with low-grade gliomas." (PMID 33859939, 2021). "The value of TAU as a biomarker for disease-free survival rate in glioma (TCGA data set) was shown by comparing the bottom and top 20% MAPT transcript expressers." (PMID 33207722, 2020). "Our in silico data show a striking inverse correlation between the expression of some of the neurodegenerative genes, especially Tau/MAPT, and the clinical progression of gliomas." (PMID 31551755, 2019). "In accordance with our previous data, gliomas with high levels of Tau/MAPT have a much better prognosis." (PMID 31551755, 2019). "Among the studied genes, we decided to focus on Tau/MAPT, as it shows the strongest correlation with the clinical evolution of gliomas." (PMID 31551755, 2019). "The protein-protein interaction (PPI) network analysis showed that ANXA5, STAT1, CD44, CAV1, ANXA2, and MAPT may serve as candidate biomarkers in glioma diagnosis." (PMID 40607003, 2025). "Tau (MAPT) has recently emerged as a novel glioma molecular target." (PMID 40806525, 2025). "A recent study has shown that high levels of MAPT correlate inversely with glioma aggressiveness." (PMID 34523079, 2021). "In addition, MAPT can alter the characteristics of the glioma mesenchyme by inhibiting EGFR-mediated NF- κB and TAZ signaling pathways, inhibit the transformation of tumor cells into pericytes, normalize tumor blood vessels, and reduce the invasiveness of gliomas." (PMID 35441059, 2022). "Evidence that transcription alterations for genes associated with neurodegeneration—with the exception of MAPT—are not common drivers of gliomas was confirmed in another study, suggesting an important role of TAU in slowing down or preventing the clinical evolution of these tumors." (PMID 33207722, 2020). "In fact, the higher expression of Tau/MAPT in lower degree gliomas suggest that it could be an accumulation of this protein in the so-called Proneural tumors, which have a better prognosis and tend to suffer a process of mesenchymalization after tumor recurrence." (PMID 31551755, 2019). "In summary, a systematic bioinformatics analysis of DEGs demonstrated that ANXA5, STAT1, CD44, CAV1, MAPT, and ANXA2 might serve as potential biomarkers and therapeutic targets for glioma." (PMID 40607003, 2025). "Finally, six genes (ANXA5, STAT1, CD44, CAV1, MAPT, and ANXA2) with the highest degree values were selected as the hub genes for glioma by using the cytoHubba plugin for expression level and prognosis analyses." (PMID 40607003, 2025). "Generally, these results suggested that ANXA5, STAT1, CD44, CAV1, MAPT, and ANXA2 might play a critical role in the pathogenesis of glioma, suggesting that the hub genes might be a promising biomarker of glioma." (PMID 40607003, 2025).
glioma (continued). "Altogether, these findings suggested that ANXA5, STAT1, CD44, CAV1, MAPT, and ANXA2 might play a vital role in the pathogenesis of gliomas." (PMID 40607003, 2025). "Hence, the mechanism of how ANXA5, STAT1, CD44, CAV1, MAPT, and ANXA2 contributed to the gliomas still need further research." (PMID 40607003, 2025). "The microtubule-associated protein TAU is highly expressed in IDH-mutant gliomas, which is detrimental to gliomas without EGFR mutations because it inhibits angiogenesis." (PMID 38365669, 2024).
neuroblastoma (16 papers, 2009 to 2025). Neuroblastoma (NB) is the most common solid, extracranial childhood tumor. "Overexpression of miR-92a-3p, one of the miRNAs identified to interact with microtubule-associated protein tau mRNAs, significantly reduced tau protein levels in neuroblastoma cell lines." (PMID 40766177, 2025). "Genes modulated after MAPT KO in neuroblastoma cells (PAGANETTI_TAU_KO_VS_WT) were associated with MAPT expression in multiple cancer types." (PMID 37730697, 2023). "We further analysed the expression of differentiation-related genes (SYP, NEFL, ENO2, MAPT) in high-risk neuroblastoma patients and correlated them to HIF1A expression." (PMID 34557995, 2022). "We also included a geneset containing the top 100 genes dysregulated in MAPT KO neuroblastoma cells when compared to Tau-expressing neuroblastoma cells." (PMID 37730697, 2023). "In another study GMC-ITC from the seeds of M. oleifera significantly decreased the expression of BACE1, APP and increased the expression of MAPT tau genes in H2O2 induced cytotoxic neuroblastoma cell (SH-SY5Y)." (PMID 37554984, 2023). "Our signature of upregulated genes in MAPT knock-out neuroblastoma cells (PAGANETTI_TAU_KO_VS_WT_UP) showed an analogous pattern of association." (PMID 37730697, 2023). "Recently, Garcìa-Escudero and colleagues detected a novel MAPT mRNA species retaining part of intron 12 (TIR-MAPT, Truncated by Intron Retention MAPT) both in human neuroblastoma cells (SH-SY5Y line) and in human brain RNA samples." (PMID 36499709, 2022). "Analysis of the bottom and top 20% MAPT expressers in pediatric neuroblastoma revealed a better prognosis for the top quintile according to the MAPT transcript analyzed on microarray (NCBO BioPortal)." (PMID 33207722, 2020). "Initially, the catalytic activities of all the designed DNAzymes against MAPT mRNA were screened in SH-SY5Y neuroblastoma cells by transfecting at two different concentrations (400 and 50 nM) for 24 h." (PMID 32575375, 2020). "As expected, neuroblastoma lines harbored the highest MAPT gene expression." (PMID 40319030, 2025). "Thus, gene modulation after MAPT KO in the neuroblastoma cell line was recapitulated in the MAPT-gene correlation analysis in brain cancer clinical samples." (PMID 37730697, 2023). "In order to specifically assay the expression of the transgenic pMAPT on the background of the endogenous MAPT in our human SK-N-F1 neuroblastoma cell culture model, we introduced a short haemagglutinin (HA) tag in-frame in exon 5 to act as a unique RT-PCR primer site." (PMID 29084565, 2017). "Previously we observed that ZMYND8 remarkably alters the transcription of several neuronal differentiation markers, including MAPT, upon ATRA-treatment in neuroblastoma cells." (PMID 36064715, 2022).
proteinopathies (16 papers, 2012 to 2025). "Further, a MAPT mutation has been reported with various comorbid pathologies that include TDP-43 proteinopathy." (PMID 38613823, 2024). "Detailed neuropathological studies have elicited proteinopathies defined by inclusions of hyperphosphorylated microtubule-associated protein tau, TAR DNA-binding protein TDP-43, fused-in-sarcoma or yet unidentified proteins in affected brain regions." (PMID 22890575, 2012). "The presence of endogenous MAPT orthologs and the demonstrated capacity to induce taupathies in cultured neurons suggest that Aplysia SN may also offer an effective screening tool for the effects of hallmark AD proteinopathies on neurons." (PMID 34664226, 2022). "To evaluate the ability of TDP‐43_SAA to detect TDP‐43 proteinopathies, we compared 30 patients with GRN and C9orf72 mutations with the other 29 subjects of the cohort (including the 27 CTRLs and the 2 patients with MAPT mutations)." (PMID 41399249, 2025). "MAPT and SNCA gene variants have been shown to be correlated with each other in the etiology of various proteinopathies." (PMID 38528629, 2024). "At the neuropathology level, GRN mutations, in contrast to those of MAPT gene encoding tau, are associated with FTLD-TDP proteinopathy." (PMID 36611365, 2022). "Results suggest that being a carrier of mutations in MAPT, TARDBP, and TREM2 triggers and accelerates the development of FTD proteinopathies that, eventually, yield a more pronounced effect on the the cognitive, behavioral, and brain tissue impacts associated with FTD." (PMID 36474176, 2022).
prostate carcinoma (13 papers, 2019 to 2025). A carcinoma that arises from epithelial cells of the prostate gland. "MAPT, mainly expressed in neuronal cells, lymphocytes, and epithelial cells, is associated with survival in prostate cancer and promotes bicalutamide resistance." (PMID 33816550, 2021). "MAPT expression is a moderate and independent prognostic factor in prostate cancer, which is particularly linked to PTEN-deleted cancers." (PMID 30823906, 2019). "Indeed, 4a-L was identified in searches of MAPT orthologs mostly in primates and a few mammals but found experimentally only in prostate cancer cell lines where microtubules are mostly associated with cell division." (PMID 41229558, 2025). "Additionally, MAPT (degree = 65) is correlated with microtubule assembly and stabilization, which can promote bicalutamide resistance and is associated with survival in prostate cancer." (PMID 34899291, 2021). "Research has found a correlation between MAPT expression levels and tumor aggressiveness in specific cancers, such as breast and prostate cancer." (PMID 39600313, 2024). "Aberrant expression of the closely related MAPT has been recently observed as an independent prognostic feature in prostate cancer." (PMID 38310601, 2024). "The aberrantly expression of MAPT is an independent prognostic factor in prostate cancer, and its knockdown can reduce cell growth." (PMID 36419120, 2022). "MAPT plays an important role in the assembly of tubulin and stabilization of microtubules, which act as protective factors in renal and prostate cancers." (PMID 34262594, 2021). "The prognostic role of MAPT in prostate cancer and childhood blastoma were also proposed in some studies." (PMID 33859939, 2021). "Previous study reported that higher expression of MAPT was detected in metastatic compared to primary prostate cancer patients." (PMID 34299042, 2021). "This study was inspired by the presence of methylation in the MAPT promoter in AD, PD as well as prostate cancer." (PMID 33207722, 2020). "Other somatic mutations associated to prostate cancer include PTEN genomic deletions, which positively associate to TAU expression with the highest MAPT transcription observed in ERG positive cancers." (PMID 33207722, 2020). "In this study, MAPT expression was analyzed by immunohistochemistry on a tissue microarray containing 17,747 prostate cancers." (PMID 30823906, 2019). "The extensive molecular database attached to our TMA allowed us to further study the role of MAPT expression in prostate cancer and to search for possible interactions." (PMID 30823906, 2019). "The results of our study identify MAPT overexpression as a moderate prognostic feature occurring in a relatively small subset of prostate cancers." (PMID 30823906, 2019). "Furthermore, a generalized linear mixed model identified statistically significant associations between prostate cancer risk and SNPs in IL12RB2, IL13, IL17A, IL4R, MAPT, and TFNRS1B." (PMID 37108754, 2023). "In prostate cancer, MAPT was reported to mediate bicalutamide resistance." (PMID 35252219, 2021). "Only one study has analyzed MAPT expression by IHC in prostate cancer before." (PMID 30823906, 2019). "The results of our study identify MAPT, as a moderate prognostic marker in prostate cancer, whose clinical impact, however, may be limited due to the rarity and heterogeneity of its expression." (PMID 30823906, 2019). "Microtubule-associated protein Tau (MAPT) overexpression has been linked to poor prognosis and decreased response to taxane-based therapies in several cancer types, but its relevance in prostate cancer is unknown." (PMID 30823906, 2019). "However, MAPT might be of interest in prostate cancer since overexpression has been found to represent a prognostic marker in several cancers." (PMID 30823906, 2019). "The association between high TAU expression and poor overall survival was confirmed in an independent study also describing an inverse interaction between MAPT and PTEN in prostate cancer." (PMID 33207722, 2020).
prostate carcinoma (continued). "Here, we employed a large - more than 17,000 prostate cancers - and highly annotated tissue microarray (TMA) to elucidate the role of MAPT expression in this disease." (PMID 30823906, 2019). "It would be interesting to study the relationship between expression of proteins related to the microtubules system - such as MAPT and TUBB3 - and response to taxanes in prostate cancer in clinical trials." (PMID 30823906, 2019). "Only a few studies demonstrated MAPT expression in prostate cancer cell lines and in clinical samples but did not attempt to link MAPT expression to clinical features of the disease." (PMID 30823906, 2019). "In this study, detectable MAPT expression was seen in about 8% of prostate cancers whereas normal prostate tissues remained negative under the selected experimental conditions." (PMID 30823906, 2019).
COVID-19 (12 papers, 2020 to 2025). A disease caused by infection with severe acute respiratory syndrome coronavirus 2. "Co-localization analysis identified LZTFL1, MUC4, OAS1, HLA-C, SLC22A31, FDX2, and MAPT as genes involved in COVID-19-mediated causation of MM." (PMID 38400850, 2024). "Two protein-coding genes, CCR5 and MAPT, are novel susceptibility genes for COVID-19, which were implicated by mQTL of Hannon blood and mQTL of LBC-BSGS blood, respectively." (PMID 34557504, 2021). "Further bioinformatic analysis revealed 8 core targets (EGFR, AR, ESR1, MAPK8, MDM2, EZH2, ERBB2 and MAPT) in the VitD-COVID-19-osteoporosis network." (PMID 36307516, 2022). "In addition to these chromosomes, the causal SNPS of COVID-19 hospitalization on MM are also located in many regions of chromosome 19, involving genes such as PSG5, SLC22A31, FDX2, MAPT and others." (PMID 38400850, 2024). "Therefore, further exploration is warranted to fully understand the relationship between COVID-19 and neurodegeneration, taking into account potential indirect pathways involving MAPT." (PMID 37286376, 2023). "Although it is tempting to establish direct connections between COVID-19 and neurodegeneration through MAPT, it is important to consider that these links could also be indirect." (PMID 37286376, 2023). "Recent studies have also related serum biomarkers to COVID-19 severity and mortality, including neurofilament light chain (NfL), glial fibrillary acidic protein (GFAp), total TAU (Microtubule-Associated Protein Tau, MAPT), and Ubiquitin carboxy-terminal hydrolase L1 (UCH-L1)." (PMID 36362378, 2022). "Together, our SMR analysis and TWAS of COVID-19 identified a total of 14 genes associated with COVID-19, comprising seven genes implicated by the input or previous GWASs and seven novel genes (including three protein-coding genes, CCR5, MAPT, and PIGN)." (PMID 34557504, 2021). "Among these overlapping genes, nonsynonymous SNPs in the exons across SPPL2C, CRHR1, MAPT, STH, and KANSL1 genes were identified, among which, 13 were from COVID-19 critical illness and 15 were from COVID-19 hospitalization." (PMID 39764106, 2024). "Together, our SMR and TWAS analyses identified three novel protein-coding genes for COVID-19, namely, CCR5, MAPT, and PIGN." (PMID 34557504, 2021). "The analysis of COVID-19 extended interactome indicates several membrane bound gene/proteins (i.e., ICAM1, EGFR, ERBB2, APP, ADR2, FAS, CDH1, and MAPT), whose activity and/or expression could be affected by SARS-CoV-2 challenge." (PMID 33123533, 2020).
depression (11 papers, 2017 to 2025). "E2F5 messenger RNA was recently proposed as a target for 3 anxiolytic microRNAs, while plasma tau (MAPT) has shown association with measures of depression in older, cognitively intact adults." (PMID 40697488, 2025). "GSK3β is closely associated with the AD proteins PS2 and MAPT and with the depression‐related proteins NR3C1 and DKK‐1." (PMID 37501340, 2024). "Notable nodes that appeared over at least two models included C9orf72, TREM2, APP and MAPT with relationships to input nodes of musculoskeletal and joint disorders, deafness and depression." (PMID 38383858, 2024). "MAPT G389A was previously reported to affect a 17-year-old girl with the initial symptoms of atypical depression and emotional blunting and a 21-year-old woman with the initial symptom of postpartum depression." (PMID 34720994, 2021). "Identification of SPI1 and MAPT as genes for AUD are good examples of pleiotropy and/ or causal links between the alcohol intake and susceptibility to AUD, other psychiatric disorders (e.g., depression), and even Alzheimer’s disease and other neurodegenerative diseases." (PMID 34417470, 2021).
ovarian carcinoma (11 papers, 2013 to 2023). A malignant neoplasm originating from the surface ovarian epithelium. "On the other hand, collagen type I is considered as involved in inducing chemoresistance by upregulating microtubule associated protein tau in paclitaxel resistant ovarian cancer cell lines." (PMID 30257426, 2018). "Expression of class I, III, and IV α- and β-tubulins and microtubule associated protein tau (MAPT, tau) has been associated with paclitaxel resistance in specimens of ovarian carcinoma." (PMID 25658796, 2015). "Expression of the microtubule associated protein tau has recently been proposed as a predictor of response to paclitaxel in ovarian carcinoma patients." (PMID 25658796, 2015). "The aim of the study was to evaluate predictive and prognostic significance of microtubule-associated protein Tau in epithelial ovarian cancer (EOC) patients treated with paclitaxel and platinum-based chemotherapy." (PMID 23631819, 2013). "MAPT gene transcription and Tau protein expression are altered in several cancers, such as breast, prostate, ovarian cancer and gliomas." (PMID 34830972, 2021). "Among them, 306 gene–tissue pairs are overlapped for the breast–ovarian cancer pair, and the tissues involved are scattered; however, a number of genes are almost concentrated in the clumping region of rs4277389 on chromosome 17, such as CRHR1, LRRC37A, and MAPT." (PMID 36819030, 2023).
synucleinopathies (11 papers, 2014 to 2025). "Furthermore, the presence of MAPT H1 haplotype is associated with an increased risk of synucleinopathies such as PD and potentially DLB and MSA." (PMID 39107835, 2024).